NTRK2 (neurotrophic receptor tyrosine kinase 2)
Diseases named in the same sentence as NTRK2 in open-access papers (continued):
Sharing a sentence is not in itself a finding about the gene and the disease.
tumor (continued). "The mRNA expression levels of NTRK2/3 were significantly (P-value <.0001) downregulated in tumour samples." (PMID 40061872, 2025). "The significant increase in NTRK2 expression indicates its possible participation in pathways vital for the survival of tumours, particularly those that are HER2-negative in BC." (PMID 40061872, 2025). "The expression of pERK, pAKT, pSTAT3, and pS6 was verified in primary tumor tissue from the ATG16L1::NTRK2 fusion-positive case." (PMID 39326005, 2025). "Screening for other molecular tumor-driving alterations revealed a novel ATG16L1::NTRK2 fusion, which contributed to oncogenicity by activating the MAPK and PI3K pathways." (PMID 39326005, 2025). "Taken together, these results indicated that the tumor became less reliant on the TRIM24::NTRK2 oncogenic driver over time and had the capacity to activate other oncogenic signaling pathways." (PMID 41331048, 2025). "A tumour with the KIF5A::NTRK2 fusion that developed in the right lateral and 3rd ventricles of patient #2 (15 y/F) exhibited features of a LG MGNT." (PMID 39014476, 2024). "Next, we selected NTRK2 as the hub gene, and in vitro experiments confirmed that its inhibition can significantly inhibit the proliferation and migration of tumor cells and promote late apoptosis." (PMID 39351154, 2024). "Despite these challenges, our study of twelve tumours harbouring NTRK1 or NTRK2 fusions revealed strong correlations and consistent positive results across various fusion partners." (PMID 39014476, 2024). "MiR-204 is known as a tumor suppressor that targets multiple oncogenes, including MYCN, BCL2, NTRK2 and PHOX2B, which are associated with tumor progression and chemoresistance in NB." (PMID 39594898, 2024). "Neurotrophic tyrosine receptor kinase (NTRK) fusions are validated oncogenic drivers of various adult and pediatric tumor types, including NTRK1, NTRK2, and NTRK3, which encode the TRK proteins TRKA, TRKB, and TRKC, respectively." (PMID 37188179, 2023). "Re-biopsy after disease progression showed that the tumor cells carrying rearranged NTRK2 were eliminated and the tumor cells with amplification of PDGFRA survived." (PMID 35135556, 2022). "FISH analysis with a break-apart NTRK2 probe confirmed the NTRK2 rearrangement in tumor cell touch preparation." (PMID 36531047, 2022). "NTRK fusions: NTRK1, NTRK2, and NTRK3 are actionable drivers of tumor growth, and these genes encode the tropomyosin receptor kinase (TRK) family of receptor tyrosine kinases, proteins TRKA, TRKB, and TRKC, respectively." (PMID 33673070, 2021). "Tumor-associated genes on Chr9q such as FANCC, NTRK2, SYK, and NOTCH1 were amplified; amplification of BRAF, EZH2, MET, CDK6 and HGF located on Chr7 were also detected." (PMID 34895266, 2021). "We investigated all patients for fusions with FGFR, neurotrophin tyrosine receptor kinase (NTRK), and MET and identified NTRK2 in one patient with a MGMT‐methylated tumor and FGFR3‐TACC3 in 3 patients (2.8%) all of which were in MGMT‐unmethylated tumors." (PMID 32885540, 2020). "Additionally, our meta-analysis revealed that NTRK2 is strongly associated with ITGAV, the other key player in tumor metastasis." (PMID 40133476, 2025). "The upregulation of both NTRK1 and NTRK2 could imply that it contributes to the progression of PR+ tumours or affects their response to hormonal therapies." (PMID 40061872, 2025). "CRISPR knockout of the TRIM24::NTRK2 fusion gene also showed tumor reliance on the VEGFR pathway." (PMID 41331048, 2025). "The identification of NTRK1 and NTRK2 upregulation among patients diagnosed with ER+ BC implies that upregulation in ER+ patients may play a role in facilitating tumour survival or growth within this subtype." (PMID 40061872, 2025). "Using biochemical experiments and GRN analysis, we propose SOX2 as an upstream regulator of NTRK2, targeting the PI3K pathway to control cell growth, while NTRK2 may play a pivotal role in tumor metastasis through interaction with E-cad." (PMID 40133476, 2025).
tumor (continued). "In salivary ACC, SCs have been shown to promote PNI by inducing the epithelial-to-mesenchymal transition (EMT) and the Schwann-like differentiation of tumor cells through the brain-derived neurotrophic factor (BDNF)–neurotrophic receptor tyrosine kinase 2 (NTRK2/TrkB) pathway." (PMID 38334648, 2024). "And we also demonstrated significant overexpression of NTRK2 in tumor tissue using the SPH cohort." (PMID 39351154, 2024). "The TRK family includes TRKA, TRKB, and TRKC proteins, encoded by the neurotrophic receptor tyrosine kinase 1 (NTRK1), NTRK2, and NTRK3 genes, respectively, and these NTRK gene fusions are oncogenic drivers of various adult and pediatric tumor types." (PMID 36770611, 2023). "Interaction between GBM cells from the secretion of BDNF and the neurotrophic receptor tyrosine kinase 2 (NTRK2) expressed on GSCs has contributed to the paracrine effect, ultimately promoting malignant progression through enhanced tumour growth and development." (PMID 37686652, 2023). "NTRK2-KO tumours exhibited fewer cells that responded to glutamate." (PMID 37914930, 2023). "Because HER2, IGF1R, MET and NTRK2 are also present in tumor-derived exosomes that play important roles in tumor progression, we aimed to investigate whether RAB31 control these RTKs entry into CD63-positive MVEs." (PMID 32958903, 2021). "NTRK gene fusions involving NTRK1, NTRK2 and NTRK3 (encoding receptor proteins TRKA, TRKB and TRKC, respectively) are responsible for many neoplasms in both adults and children, including rare cancers such as secretory breast carcinoma and infantile fibrosarcoma." (PMID 33921237, 2021). "For example, tumor-agnostic biomarkers such as micro-satellite instability, oncogenes like NTRK1, NTRK2, and NTRK3, and the recently United States Food and Drug Administration (FDA)-approved tumor mutation burden, are used for tumor-agnostic patient stratification and therapeutic decisions." (PMID 33396205, 2020). "In addition to TRIM24::NTRK2 and CDKN2A/B HD, a SLC6A14 missense variant (p.R614H) of unknown significance (VUS) was present in all six tumor specimens." (PMID 41331048, 2025). "As a result, we observed that neuron-related genes (CNTN1, FAT3, PTPRG, NTRK2, etc.)annotated to categories such as nervous system development, neuron differentiation, generation of neurons, and neurogenesis were downregulated in tumor cluster cells (Online Resource)." (PMID 38609519, 2024). "For NSCLC, recommendations comprised larotrectinib/entrectinib (unconventional SLC28A3::NTRK2 gene fusion), capmatinib (MET amplification, GCN: 16.7), afatinib (RBPMS::NRG1 gene fusion), and dabrafinib/trametinib in the case of a BRAF p.Val600Glu, and a non-V600E BRAF mutated tumor, respectively." (PMID 38136436, 2023). "NTRK1, NTRK2, and NTRK3 gene fusions are rare oncogenic driver alterations found in diverse tumor types of adults and children." (PMID 40385986, 2025). "Some DEGs like FREM2, ANXA2 and GPC4 revealed common enrichment in LE/IT tumor regions across GBM patient samples compared to the overall downregulation of the OPC/OL marker MBP, the neural marker NTRK2, and the ECM glycoprotein EDIL3." (PMID 41366031, 2025). "Utilizing a published scRNA-seq dataset comprising 15 tumor samples and one nasopharynx, UMAP visualization revealed that SOX2, NTRK2, LRP6, and PTPRZ1 from our candidate list were predominantly expressed in epithelial and malignant patient cells." (PMID 40133476, 2025). "Upon progression, a second partial resection was followed by DNA methylation profiling, which reclassified the tumor as a glioneuronal tumor with ATRX alteration, kinase fusion, and anaplastic features (GTAKA), harboring a KANK1::NTRK2 fusion." (PMID 41397922, 2025). "Patient #3, a 3-year-old female with GKAP1::NTRK2-fused LGG in the right thalamus and 3rd ventricle, underwent adjuvant larotrectinib treatment for residual tumour." (PMID 39014476, 2024).
tumor (continued). "This gene family encodes tropomyosin receptor kinases (TRKA, TRKB, and TRKC), and fused NTRK genes (NTRK1, NTRK2, NTRK3) translate a TRK fusion protein that activates tyrosine kinases and constitutively stimulates the growth of tumor cells." (PMID 37895255, 2023). "Other than that, LMP1 upregulates neurotrophic tyrosine kinase receptor type 2 (NTRK2 or TrkB) expression to enhance anoikis resistance, which is necessary for survival after detachment from the tumour, of NPC cells through NF-κB signalling." (PMID 36846758, 2023). "Examples of genes that are strongly correlated with NTRK2 in the astrocyte-like compartment include GJA1, TTHY1, GRIK1 and KCNN3; TTHY1 and GJA1 are known to have crucial roles in tumour microtube formation and connectivity in adult high-grade gliomas." (PMID 37914930, 2023). "Fusions of neurotrophic tropomyosin receptor kinase genes NTRK1, NTRK2 and NTRK3 with various partner genes have been detected in a variety of both common and rare tumour entities." (PMID 34372873, 2021). "However, NGS (OncomineTM Comprehensive Assay v3/Archer FusionPlex Salv GlandDx Panel) performed on the fresh tumor tissue still showed the known NTRK2 fusion, no mutation in the kinase domain, and no other alterations, particularly for genes in the mitogen-activated protein kinase pathway." (PMID 33530256, 2021). "NTRK1, NTRK2 or NTRK3 can be found as oncogenic drivers in a wide range of paediatric and adult tumours." (PMID 33620682, 2021). "Druggable fusion events were identified in 7.1% (5/70) of tumor specimens: FGFR3-TACC3 (n = 2), NTRK2 fusions (n = 1), ALK (n = 1), and ROS1 (n = 1)." (PMID 34234122, 2021). "For example, we found six cancer types with a single fusion in a gene of the NTRK family, but altogether, we detected a total of 23 NTRK1, NTRK2 and NTRK3 fusions across nine tumour types." (PMID 25204415, 2014). "PCR amplification from patient cDNA across the duplicated region confirmed the presence of NTRK2 ITD and wild type (WT) NTRK2 transcript and pan-TRK immunochemistry (IHC) confirmed high-intensity extranuclear staining in the tumor, compared to control staining (normal brain)." (PMID 40348911, 2025). "Additionally, we examined the levels of NTRK2 and NTRK3 expression in patients diagnosed with BC who had tumours positive for HER2." (PMID 40061872, 2025). "This hypothesis was supported by our snRNA-seq analysis, in which we clearly observed that genes related to neuronal migration and axon guidance (CNTN1, PTPRG, NTRK2, FAT3, etc.)were more upregulated in neuron cell clusters than in tumor cell clusters." (PMID 38609519, 2024). "Somatic intrachromosomal or interchromosomal rearrangements involving NTRK1, NTRK2, or NTRK3 may be found as oncogenic drivers in a wide range of tumor types." (PMID 39295960, 2024). "In tumours, CSF1R correlated with AXL, EPHA2 with PGFRA, and NTRK2 with PGFRB and AXL." (PMID 36890818, 2023). "In tumours, a strong, significant and positive correlation was recorded between PGFRB and NTRK2." (PMID 36890818, 2023). "Among the other two tumors with strong Pan-TRK expression, the NTRK1, NTRK2 or NTRK3 rearrangement was negative in one tumor (case #4), and no rearrangement was evaluated because of the poor DNA quality in the other sample (case #5)." (PMID 36612101, 2022). "Non-BRAF alterations were detected in four tumor samples consisting of CLIP2:NTRK2, KANK1:NTRK2, RAF1:QKI, and KRAS Q61H." (PMID 36163281, 2022). "Tumor samples from 31 patients were tested for NTRK1, NTRK2, and NTRK3 fusion by FISH analysis." (PMID 35681640, 2022). "RT-PCR analysis of tumor RNA with primers specific for LHFPL3 and NTRK2 showed 3 bands." (PMID 36531047, 2022). "Fusions of neurotrophic tropomyosin receptor kinase genes NTRK1, NTRK2 and NTRK3 with various partner genes occur in both common and rare tumours and are of paramount predictive value due to the availability of very effective pan-Trk inhibitors like Larotrectinib and Entrectinib." (PMID 34372873, 2021).
tumor (continued). "This oligo-like tumor presented with microvascular proliferation, without necrosis, and 6 mitoses for 2.3 mm2, and harbored an NTRK2 rearrangement by FISH [ZytoLight SPEC NTRK2 dual color break apart probe (Zytovision, Bremerhaven, Germany)]." (PMID 31677015, 2020). "Taken together, comparison of BDNF growth factor and NTRK2 receptor gene expression with clinical data revealed that BDNF is produced both in stroma and in tumor cell nests of HNSCC, the availability of the NTRK2 gene product, TrkB, is limited to approximately 40% of the cases." (PMID 30641914, 2019). "Similarly, genes such as CAV1, ACACB, NTRK2, KLF4, and MYH11 were the key down-regulated hub genes suggesting a possible role of their decreased expression in breast carcinogenesis." (PMID 31292488, 2019). "When methylation values were compared within individual pairs of PN and PT samples, significantly higher methylation levels of PAPSS2 TUBG2, NTRK2, and SFRP4 were found in 60% (18/30), 50% (15/30), 30% (9/30), and 36% (11/30), respectively, in PN than in corresponding tumor samples (PT)." (PMID 19662090, 2009). "However, our results point to TRIM24::NTRK2 not being the only driver in this tumor, but is likely a combination with CDKN2A/B HD, pTERT, and other acquired alterations in later relapses." (PMID 41331048, 2025). "This binding triggers the tumor cells to release brain-derived neurotrophic factor (BDNF), which enhances cancer innervation via activation of host neurotrophic receptor tyrosine kinase B receptors (NTRK2), thereby establishing a feed-forward loop of sustained signaling." (PMID 40359002, 2025). "No expression was detected for NTRK2 in both normal and tumour tissues." (PMID 40061872, 2025). "We report ZBTB43::NTRK2 as a new fusion that has not been previously reported in any tumour." (PMID 39014476, 2024). "Moreover, according to a bioinformatics analysis of differentially expressed genes between luminal B2 breast cancer tumor and nontumor tissues, NTRK2 participates in tumor-promoting pathways, focal adhesion, and ECM-receptor interactions and plays a leading role in tumorigenesis." (PMID 35383130, 2022). "Moreover, this tumor was negative for NTRK2 and NTRK3 rearrangements." (PMID 36612101, 2022). "The NTRK2 gene was not examined by FISH, but NTRK2 gene fusions are reported to be even much rarer than NTRK1 and NTRK3 gene rearrangements in other neoplastic diseases." (PMID 40235191, 2025). "Another tumor (case #7) with weak-moderate expression of Pan-TRK was negative for NTRK1, NTRK2 and NTRK3 rearrangements." (PMID 36612101, 2022). "Polyploidy was detected in most tumor cells using the NTRK1 break-apart probe in case #6, but no rearrangement of NTRK1, NTRK2, or NTRK3 was detected using the three break-apart probes." (PMID 36612101, 2022).
cancer (206 papers, 2008 to 2026). A tumor composed of atypical neoplastic, often pleomorphic cells that invade other tissues. "Scenarios include NTRK fusion genes, such as NTRK1, NTRK2, and NTRK3 (encoding tropomyosin receptor kinases, TrkA, TrkB, and TrkC, respectively), that link the tyrosine kinase domain with a 5’ fusion partner (over 50 partners across cancers)." (PMID 39956859, 2025). "Among the four largest clusters with >100 reported PPI-based MPP communities, the cluster with 135 communities, such as BDNF/NT-3 growth factor receptor (encoded by NTRK2), was broadly linked to the most pathways relevant to cancer hallmarks." (PMID 31311925, 2019). "Rare mutated versions of the NTRK2 gene, which encode proteins consisting of fusions of the TrkB kinase domain with domains of other signaling proteins, are drivers in a number of cancers." (PMID 31221127, 2019). "Their analysis shows that NTRK2 has a somatic mutation frequency of 0.4% in cancer patients." (PMID 34290315, 2021). "One NTRK2-encoded protein is TrkB-FL, which can regulate multiple pathways relevant to cancer." (PMID 31221127, 2019). "NTRK fusions, which result from rearrangements in the NTRK1, NTRK2, or NTRK3 genes (encoding TRKA, TRKB, and TRKC, respectively), are actionable oncogenic drivers found in a diverse range of adult and pediatric cancers." (PMID 41492362, 2026). "The TRK family, comprising TrkA, TrkB, and TrkC, encoded by NTRK1, NTRK2, and NTRK3, respectively, has emerged as a critical therapeutic target in cancer." (PMID 39860039, 2025). "The volcano plot further confirmed the importance of these genes by pinpointing significantly upregulated and downregulated genes, such as TP63, NTRK2, and CLCA2, which are strongly associated with cancer." (PMID 40370696, 2025). "NTRK gene fusion-positive tumours are cancers with specific genetic abnormalities involving NTRK genes (NTRK1, NTRK2, NTRK3), which encode tropomyosin receptor kinase (TRK) proteins A, B, and C." (PMID 40141188, 2025). "Notable downregulated genes included Mki67, Ccn1, Muc1, Atf3, Ntrk2, Arid5b, Igf1r, Igf2bp2, Cd47, and Cd37 (oncogenic function) and integrin-related genes, Itga7, Itga11, Itgam and Notch1 (cancer stem cell markers)." (PMID 39946195, 2025). "On the other hand, brain-derived neurotrophic factor (BDNF) and neurotrophin-4/5 bind to TrkB and atypical activation of TrkB due to mutations or fusions involving NTRK2 can contribute to oncogenic transformation in certain cancers." (PMID 39124968, 2024). "E2F1 and CHEK2 were highly expressed across most cancer types compared to normal samples, while PDK4 and NTRK2 were decreased in various cancers." (PMID 36937870, 2023). "TRKB receptors, also known as TrkB or NTRK2, play a significant role in cancer development and progression." (PMID 37445902, 2023). "A number of cancers have also been shown to overexpress promyosin-related kinase B (TrkB, also known as NTRK2), a powerful and selective inhibitor of anoikis." (PMID 37114037, 2023). "Many targets, including PDGFR, CD44, CSF1R and NTRK2, have small-molecule inhibitors approved for clinical use or are currently under clinical trials for cancer treatment, including glioblastoma." (PMID 36216799, 2022). "Neurotropic tropomyosin receptor kinases (NTRK1, NTRK2, and NTRK3) encode tyrosine receptor kinases (TRKA, TRKB, and TRKC), which induce many types of cancer pathogenesis through the activation of downstream signaling." (PMID 35008821, 2021). "Recent research advancement in the field revealed the relationship between NTRK2 and cancer biology." (PMID 31245181, 2019). "Two other genes included in the associated loci, Myosin VA (MYOVA) gene on chromosome 15 and Neurotrophin tyrosine kinase receptor 2 (NTRK2) on chromosome 9, are both overexpressed in cancer." (PMID 25629528, 2015). "NTRK2 fusions are rare across nearly all cancers, with an overall prevalence of just 0.05%." (PMID 39773366, 2025).